AR (androgen receptor)
Diseases named in the same sentence as AR in open-access papers (continued):
Sharing a sentence is not in itself a finding about the gene and the disease.
prostate carcinoma (continued). "DNPC is currently classified as AR negative prostate cancer without overt NE differentiation markers." (PMID 38667288, 2024). "Additionally, the identification of bromodomain-containing 7 (BRD7), a negative regulator of cell proliferation and growth, represses the AR transactivation activity induced by TRIM24 and contributing to the modulation of prostate cancer pathogenesis." (PMID 39160596, 2024). "Neuroendocrine differentiation in prostate cancer typically involves the expression of markers like neuron-specific enolase (NES), chromogranin A (CHGA), P63, and CD56, and usually lacks androgen receptor (AR) expression." (PMID 39301540, 2024). "Furthermore, ICB and other targeted therapeutic strategies, such as AR blockade and ATR kinase inhibition, worked together to produce a synergistic therapeutic response in prostate cancer." (PMID 39547513, 2024). "In a prostate cancer study, carcinogenesis which is marked by heightened activation of the IGF-1/IGF-1R axis through the PI3K/Akt or RAF/MEK/ERK signaling pathways and the expression of the androgen receptor (AR), was reduced after quercetin treatment." (PMID 38256917, 2024). "Androgens and the androgen receptor (AR) are crucial in regulating the growth and progression of prostate cancer, hence androgen deprivation therapy (ADT) is an effective treatment option for prostate cancer." (PMID 38698344, 2024). "In fact, the AR signaling axis is the major therapeutic target for BPH and prostate cancer." (PMID 39830338, 2024). "Specifically, both transdifferentiated prostate cancer cells and de novo neuroendocrine prostate cancer cells exhibit the absence of AR and prostate-specific antigen (PSA)." (PMID 38238517, 2024). "SMYD2 overexpression in prostate cancer regulates AR protein stability through the nonhistone methylation of this protein." (PMID 39482529, 2024). "The 3D scaffolds were cultured with non-functional androgen receptor (AD) PC-3 prostate cancer cell lines, bone metastasis-derived C4-2B cell lines with functional AR and human prostatic carcinoma xenograft 22Rv1 cell lines." (PMID 38791452, 2024). "Increased expression of AR in DPC and prostate cancer cells promotes cellular senescence." (PMID 39256806, 2024). "Due to the AR-mediated repression of NR3C1 expression, AR-negative prostate cancer cells exhibit higher levels of GR compared to AR-positive cells." (PMID 39027480, 2024). "The significance of GR signaling has been underscored by phenotypical experiments conducted in several AR-negative prostate cancer cell lines." (PMID 39027480, 2024). "In addition, PER1 has been reported to inhibit the transactivation of androgen receptor (AR) through direct interaction, and the ectopic expression of PER1 in human prostate cancer cells (LNCaP) reduces the expression of known AR target genes." (PMID 39012661, 2024). "The other two mechanisms of ADT resistance include the bypass mechanism, which allows AR‐dependant pathways to activate regardless of AR‐activation, and the de‐differentiation of prostate cancer cells into NEPC cells." (PMID 39410867, 2024). "This pattern indicates a shift from the typical hormone-responsive prostate cancer cells towards a phenotype that is less responsive to hormonal therapy due to the lack of AR." (PMID 39301540, 2024). "Notably, pharmaceutical agents modulating the activity of ER, AR, RAR, and GR are presently employed in the treatment regimens for breast cancer, prostate cancer, APL, and acute lymphoblastic leukemia, respectively." (PMID 39327610, 2024). "Multiple studies have demonstrated that melatonin can mediate the nuclear rejection of the AR in prostate cancer cells without inhibiting the binding capacity of androgens to the AR." (PMID 39011396, 2024). "Treatment options whose target is the AR, such as bicalutamide, a second-generation non-steroidal AR antagonist, have been widely used in prostate cancer with successful results." (PMID 39063165, 2024).
prostate carcinoma (continued). "In conjunction with TRIM33 being identified by all three interactomes, further support for investigating the role for TRIM33 in ER+ breast cancer comes from findings in prostate cancer cells where TRIM33 modulates the activity of another nuclear hormone receptor, the androgen receptor." (PMID 38473207, 2024). "High (LNCaP) and low (DU‐145) expressing AR prostatic cancer cell lines used as positive and negative controls, respectively, exhibited similar patterns of AR receptor expression to the HTB‐131 and HTB‐132 cell lines, respectively." (PMID 37903548, 2024). "Here a small subset of cells expressing CD44+/α2β1/CD133+ and lacking of AR expression are identified as prostate cancer stem cells (PCSC), and they hold the ability of proliferating even in androgen-depleted environments or under ADT." (PMID 38887275, 2024). "Actually, when compared with hormone-naïve and CRPC prostate cancer specimens, CRPC specimens with higher AR expression levels had reduced PURα m-RNA, cytosolic rather than nuclear localization of the PURα protein, and occupancy by PURα of the suppressor element in the 5′-UTR of the human AR gene." (PMID 39000020, 2024). "Furthermore, the knockdown of AR in C4-2 and LNCaP cells significantly increased H2O2 levels in prostate cancer cells and led to a significant downregulation of PMP70 levels." (PMID 39097593, 2024). "The application of next generation androgen receptor signaling pathway inhibitors (ARPIs) has led to a gradual increase of AR-negative prostate cancer in the clinic." (PMID 38254880, 2024). "Furthermore, a comprehensive analysis of OCT1 signals revealed that Acyl-CoA Synthetase Long-Chain Family Member 3 (ACSL3) was the most highly expressed gene regulated by both AR and OCT1 in hormone-responsive prostate cancer cells (LNCaP cells)." (PMID 38698344, 2024). "High CTBP2 expression levels correlate with poor prognosis in prostate cancer patients, while CTBP2 suppresses cancer-inhibiting genes and AR inhibitory factors, such as NCOR and RIP140, by binding to their transcription regulatory regions in prostate cancer cells." (PMID 38698344, 2024). "Furthermore, downregulation of SRC-1 expression inhibited the growth of prostate cancer cells and decreased the transcriptional activity of prostate-specific antigen (PSA), an AR target gene." (PMID 38553750, 2024). "Some non-AR pathways, such as the AR bypass mechanism and androgen-independent lurker cells, also contribute to the therapy resistance of prostate cancer." (PMID 38339414, 2024). "In addition, It has been reported that overexpressed Jagged1 enhances prostate cancer cell proliferation by interacting with AR, thereby promoting the development of prostate cancer, and silencing of RBPJ reduces the expression of the AR and its target genes." (PMID 38538986, 2024). "Specifically, it demonstrates significant antiproliferative activity in both androgen receptor-positive LNCaP and androgen receptor-negative PC-3 prostate cancer cell line." (PMID 39770110, 2024). "In the absence of a ligand, the androgen receptor (AR), which is responsible for prostate cancer cell proliferation, is blocked." (PMID 39123487, 2024). "CMG2 can inhibit the growth of breast cancer cells in vitro and in vivo but has little impact on the proliferation of an AR-negative prostate cancer cell line (PC-3)." (PMID 39199664, 2024). "Recent research has shown that radiation therapy in combination with the AR inhibitor enzalutamide decreases the survival of AR-positive LNCaP cells but not of AR-negative PC-3 prostate cancer cells." (PMID 39769434, 2024). "Some studies have suggested that JNK is regulated in the enlarged prostate and/or during the proliferation of prostate stromal cells, while others found that an interaction with AR triggers JNK phosphorylation and downstream signaling to facilitate cell cycle progression in BPH and prostate cancer." (PMID 39598426, 2024).
prostate carcinoma (continued). "In general, we believe Raman shows relative protein-band increases that are indicative of the prostate-cancer state irrespective of AR status." (PMID 39455589, 2024). "We showed that ARHGAP21 silencing in LNCaP prostate cancer cells decreased PCA3 and androgen receptor (AR) transcriptional levels and increased prune homolog 2 (PRUNE2) coding gene expression, indicating effective involvement of ARHGAP21 in androgen-dependent tumor pathway." (PMID 38896642, 2024). "Despite its potent effects on AR expression and activity, CDKI-73 exhibited comparable efficacy in AR-dependent and AR-negative/independent models of prostate cancer." (PMID 39117800, 2024). "First, the AR activity has been inferred by the expression of a set of ARGs that has been validated by prostate cancer, but not for glioblastoma." (PMID 38233838, 2024). "MYB silencing and the CHK1 inhibitor AZD7762 showed synergistic effects with olaparib in androgen receptor (AR)-positive and -negative prostate cancer cells." (PMID 38835346, 2024). "Furthermore, research has demonstrated that KDM5B regulates the androgen receptor and interacts with the PI3K/AKT pathway, contributing to the progression of prostate cancer." (PMID 39239542, 2024). "As expected from previous studies of PTEN KO prostate cancer models, we found that this cancer cell line was not AR-dependent, as it did not respond to enzalutamide in vivo when implanted subcutaneously in the flank of C57BL/6 males." (PMID 39591176, 2024). "It inhibits the transcriptional activity of the activated androgen receptor (AR) in prostate cancer cells without altering AR mRNA or protein levels." (PMID 39199550, 2024). "Mechanistically, menin was found to localize to multiple ECM-related genes and to suppress the expression of multiple metastasis-related genes in an AR-negative prostate cancer cell line compared to an AR-positive line." (PMID 39336822, 2024). "In vitro, androgen receptor negative and -inhibited prostate cancer cell lines were shown to increase prothrombin expression and thereby induce platelet aggregation and hypercoagulability as opposed to androgen receptor-positive prostate cancer cell lines." (PMID 39639392, 2024). "This may be due to different chromatin states between DSRCT and prostate cancer cells, or could suggest a model in which AR binds to EWSR1::WT1, resulting in AR recruitment to WT1 binding sites." (PMID 38575753, 2024). "This article focuses on lncRNAs that regulate enzalutamide resistance and the neuroendocrine transition of prostate cancer through epigenetic, androgen receptor (AR) signaling, and non-AR pathways that act as “molecular sponges” interacting with miRNAs." (PMID 39655078, 2024). "Another study based on prostate cancer reported that luteolin has been found to have a dose- and time-dependent effect on the suppression of intracellular and secreted PSA levels, as well as the repression of AR mRNA and protein expression." (PMID 38474604, 2024). "This underscores the urgent need for new therapeutic targets for AR-negative prostate cancer subtypes." (PMID 39027480, 2024). "This suggests that menin plays a tumor-suppressive role by limiting the initiation of pro-EMT transcriptional programs in AR-negative prostate cancers." (PMID 39336822, 2024). "The transformation to neuroendocrine prostate cancer (NEPC), a lethal form of prostate cancer, represents an increasing form of therapeutic resistance characterized by little or no AR activity and high levels of neuroendocrine markers." (PMID 36768610, 2023). "PC3 cells are AR negative, resistant to therapies based on androgen deprivation, highly motile, and used to study prostate cancer metastasis." (PMID 37077937, 2023).
prostate carcinoma (continued). "As a key therapeutic target, there is no doubt that AR plays an important role in prostate cancer development, metastasis and drug resistance." (PMID 37326412, 2023). "A role for AR has been proposed in many age-related diseases and the androgen/AR axis mediates, through nongenomic mechanism, the cellular senescence in prostate cancer cells." (PMID 38040692, 2023). "Given that AR-dependent transcription is a prerequisite for ERG translocation, these studies concluded that a functional CHD1 supports AR signaling transcriptome and ERG fusion development in prostate cancer." (PMID 36776288, 2023). "A particularly challenging problem is the management of AR-indifferent prostate cancers that either do not express AR from the onset of the cancer or lose AR expression during the course of systemic therapy." (PMID 37112881, 2023). "Furthermore, Western blot analysis demonstrated that saffron treatment induced changes in the expression of other key genes (DNMT1, DNMT3b, MBD2, CD44, HDAC3, c-Myc, NF-kB, TNFα, AR, N-RAS, and PTEN) in prostate cancer cells." (PMID 38201944, 2023). "In conclusion, our findings demonstrate that YIV-818A RA-V and RA-VII could effectively inhibit both DHT-driven AR activity and DEX-driven GR activity in prostate cancer cells." (PMID 37860121, 2023). "As a first step toward evaluating whether PARP7 levels in human prostate cancer are potentially actionable with RBN2397, we analyzed PARP7 gene expression data from primary prostate tumors and metastatic AR+ and AR− prostate tumors." (PMID 37077937, 2023). "Enzalutamide is a second-generation, nonsteroidal AR inhibitor that is widely used to treat prostate cancer, especially the metastatic castration-resistant form of the disease." (PMID 37894395, 2023). "Unlike the breast cancer studies, treatment with X15695 did not strongly downregulate AR level in LNCaP prostate cancer cells nor in the castration-resistant prostate cancer (CRPC) cell line 22Rv.1." (PMID 37520743, 2023). "We next asked whether suppression of AR, Myc, or the PI3K/AKT pathway is critical to the antiproliferative activity of fimepinostat in prostate cancer." (PMID 37823778, 2023). "However, the molecular mechanisms of the regulation of AR on MALT1 in androgen-dependent and -independent prostate cancer cells have yet to be clearly established." (PMID 37047218, 2023). "Additionally, AR influences various upstream mediators of autophagy, including ATG4B, ATG4D, ULK1, and ULK2, which contribute to the progression of prostate cancer." (PMID 37834333, 2023). "Suppression of androgen receptor signaling by androgen deprivation therapy (ADT), which involves blocking the production or activity of androgens, has been a major treatment approach for prostate cancer." (PMID 37104249, 2023). "Whilst this relationship is independent of the androgen receptor, both proteins are described as oncogenes in prostate cancer." (PMID 37509260, 2023). "In this study, we found that enzalutamide plus saracatinib is synergistic in prostate cancer cell lines that express AR-FL, regardless of AR-V status." (PMID 37456235, 2023). "Additionally, we aimed to explore the therapeutic potential of a combined treatment involving an androgen receptor antagonist (bicalutamide) and a XIAP inhibitor (embelin) to suppress prostate cancer growth." (PMID 37564213, 2023). "Recently, other distinct molecular subgroups of treatment-resistant tumors have been described which are either composed of tumor cells coexpressing both AR and neuroendocrine markers (amphicrine prostate cancer) or those that are double-negative for both." (PMID 37546702, 2023). "Finally, the action of androgens binding to the AR, prostate-specific antigen (PSA) levels, as well as changes in the 5α-reductase enzymes with aging/BPH and prostate cancer have been reviewed elsewhere." (PMID 36982560, 2023).
prostate carcinoma (continued). "In prostate cancer, AR-negative CAFs are known to surround cancer-cell nests and AR-negative CAFs have been reported to affect cancer growth, invasion, and stemness." (PMID 37509283, 2023). "Consistently, RIOX2 mRNA expression was observed in all prostate cancer cell lines with or without AR expression." (PMID 36776320, 2023). "It was noted that PMEPA1-e promoted the growth of AR-negative prostate cancer cells in a TGF-β-independent manner while having no impact on AR-positive prostate cancer cells." (PMID 38173834, 2023). "Increased sensitivity of AR-positive (compared to AR-negative) prostate cancer cell lines to THZ1, an inhibitor of CDK7/CDK12/CDK13, has been previously reported." (PMID 37076563, 2023). "LNCaP cells were used for the primary analysis of stromal-tumor interaction because they still represent the most typical type of prostate carcinoma due to their expression of the androgen receptor (AR) and their hormone dependence unlike other cell lines." (PMID 37671061, 2023). "The fact that 8A and 41A cannot suppress AR-null PC-3 and DU145 prostate cancer cell proliferation suggests their antiproliferative activity in the AR-positive LNCaP cell model may be associated with AR." (PMID 37111288, 2023). "Here, we use a recently developed catalytic inhibitor to PARP7, RBN2397, to study the effects of PARP7 inhibition in androgen receptor (AR)-positive and AR-negative prostate cancer cells." (PMID 37077937, 2023). "At least 50 of the almost 300 known AR co-regulators are overexpressed in prostate cancer cells, which correlates with a negative outcome and prognosis." (PMID 36746939, 2023). "While target-specific molecular glues like SMAPs are still in their early phase of development, our study suggests that combining PI3K/AKT/S6K1 pathway inhibitors with antiandrogen therapies cannot be ruled out in AR-addicted prostate cancer." (PMID 37644036, 2023). "In prostate cancer, CAFs have been reported to produce IFN-γ and macrophage colony-stimulating factors in response to the activation of AR pathways; thus, CAFs may promote PD-L1 expression in cancer cells through IFN-γ production." (PMID 37509283, 2023). "The LuCaP TMA from PDX contain 42 patient tissues (24 are from adenocarcinoma, 13 from CRPC, 4 patients are from t-NEPC and one AR null, NE null prostate cancer group often referred as double negative stage) in triplicate." (PMID 38168280, 2023). "This could explain in part why SET7/9 reportedly stimulates prostate cancer cells, namely through JMJD2D methylation, albeit this may additionally involve the methylation of the androgen receptor." (PMID 38045004, 2023). "Differently from prostate cancer, mechanistic target of rapamycin (mTOR) protein, a key member of the PI3K-AKT-mTOR signaling pathway frequently hyperactivated in several malignancies, stimulates AR transcriptional activity in HCC." (PMID 37508414, 2023). "Similar to ER, androgen receptor (AR) is mainly activated by the androgen steroid hormones testosterone and 5α-dihydrotestosterone (5α-DHT), which is the major factor promoting the proliferation of prostate cancer." (PMID 36632213, 2023). "Notably, a positive correlation between AR and FEN1 expression has likewise been observed in prostate cancer." (PMID 37326412, 2023). "Some of the non-gynecological neoplasms, such as prostate cancer which express androgen receptor (AR), have been treated with androgen antagonist for many years." (PMID 37725629, 2023). "In prostate cancer, it is shown that CCL5-derived from MSCs and cancer cells, through suppressing the nuclear translocation of androgen receptors, increases the metastatic potential of cancer cells due to inhibiting androgen receptor signaling." (PMID 38022534, 2023).